CHD4 (chromodomain helicase DNA binding protein 4)
Diseases named in the same sentence as CHD4 in open-access papers (continued):
Sharing a sentence is not in itself a finding about the gene and the disease.
ovarian carcinoma (15 papers, 2017 to 2025). A malignant neoplasm originating from the surface ovarian epithelium. "CHD4 overexpression is associated with oncogenic activity, poor prognosis, and increased risk of colorectal cancer and ovarian cancer metastases." (PMID 41417740, 2025). "For example, our list included BCL6, which displays pro-oncogenic activity in ovarian cancer, and CHD4, which is associated with apoptosis mediated by cisplatin in ovarian cancer cells." (PMID 38844966, 2024). "A high expression of CHD4 in ovarian cancer is associated with tumor metastasis and poor prognosis for patients with ovarian cancer." (PMID 37894746, 2023). "In ovarian cancer, our findings verified that the expression level of CHD4 is associated with the pathological grade and FIGO stage." (PMID 36681835, 2023). "In an analysis of the Cancer Genome Atlas ovarian cancer dataset, CHD4 gene amplification was associated with worse overall survival." (PMID 34161330, 2021). "Consistently, BRCA2 mutated ovarian cancers with reduced PAXIP1 or CHD4 expression are associated with shorter progression-free survival and shorter overall survival." (PMID 34645978, 2021). "Moreover, the chromodomain-helicase-DNA-binding protein 4 (CHD4), acting as a chromatin remodeler, seems to be associated with platinum therapy resistance in ovarian cancer." (PMID 38891056, 2024). "Loss of function of CHD4 in ovarian cancer cells induced suppression of migration and invasion." (PMID 36681835, 2023). "In ovarian cancer patient specimens, high CHD4 expression was associated with a poor prognosis." (PMID 36681835, 2023). "Importantly, a more recent study demonstrated that loss of CHD4 leads to therapeutic resistance in BRCA2 mutant ovarian cancer." (PMID 29625565, 2018). "In addition, we have identified a mutation in CHD4 using previously published RNAseq data from the ovarian carcinoma cell line SKOV-3 (H1196Y) which we have included in the analysis." (PMID 29844320, 2018). "Surprisingly, higher expressions of DNMT3B and EZH2 are reported in ovarian cancer and, as per RNA-seq results, CHD4 expression is positively correlated with EZH2 in ovarian cancer patients." (PMID 40004553, 2025). "A previous study confirmed that CHD4 promoted β-catenin accumulation in the nucleus of ovarian cancer cells." (PMID 38268032, 2024). "Strikingly, an early study mentioned that CHD4 promoted the nuclear accumulation of β-catenin in ovarian cancer." (PMID 38268032, 2024). "We investigated the clinical significance of CHD4 through TCGA and GEO database analyses and explored the effect of CHD4 expression modulation and romidepsin treatment on the biological behaviour of ovarian cancer through CCK-8 and transwell assays." (PMID 36681835, 2023). "In summary, our results highlight a novel and essential role for CHD4 in the maintenance of ovarian cancer in vitro and in vivo." (PMID 36681835, 2023). "To assess the cellular impact of reduced CHD4 expression levels, we first evaluated the baseline mRNA and protein expression levels in some ovarian cancer cell lines (SKOV3, SKOV3-ip, Hey, OVCAR3, and Caov3)." (PMID 36681835, 2023). "Collectively, our results uncovered an oncogenic function of CHD4 in ovarian cancer and provide a rationale for clinical trials of romidepsin in ovarian cancer patients." (PMID 36681835, 2023). "CHD4 induces the suppression of the migration and invasion of ovarian cancer cells by suppressing the expression of EZH2 and the nuclear accumulation of β-catenin." (PMID 37894746, 2023). "Overall, we observed that EZH2 is essential for CHD4-mediated repression of ovarian cancer tumorigenesis." (PMID 36681835, 2023). "Romidepsin, an HDAC1/2 selective inhibitor, is able to inhibit ovarian cancer metastasis through inhibiting the functions of CHD4 that are mediated by histone deacetylase." (PMID 37894746, 2023). "According to RNA-seq analyses, CHD4 was positively correlated with EZH2 in ovarian cancer patients (p = 0.004)." (PMID 36681835, 2023).
ovarian carcinoma (continued). "Here, we identified EZH2 as a cofactor for CHD4 and established the physiological significance of its interaction with CHD4 in the context of ovarian cancer progression." (PMID 36681835, 2023). "Considering that ovarian cancer has various pathologic types, CHD4 mRNA levels in different histologic types were analysed through the GEO database." (PMID 36681835, 2023). "CHD4 also suppressed the metastasis of ovarian cancer cells and prevented disease progression in a mouse model." (PMID 36681835, 2023). "Following our previous study, we identified that CHD4, a chromatin remodelling factor, plays a strong role in ovarian cancer cell metastasis." (PMID 36681835, 2023). "Western blot analysis confirmed that CHD4 knockdown suppressed P-glycoprotein expression in TOV21G as well as JHOG5 and JHOS2, suggesting that CHD4 was involved in platinum sensitivity by regulating drug efflux via P-glycoprotein in ovarian cancer." (PMID 34161330, 2021). "We further showed the potential of CHD4 as a candidate therapeutic target in combination with platinum agents for ovarian cancer." (PMID 34161330, 2021). "Taken together, these results suggest that CHD4 inhibition enhances cisplatin-mediated apoptotic cell death by promoting cytotoxic DNA damage in ovarian cancer cells." (PMID 34161330, 2021). "The purpose of this study was to clarify the role of CHD4 in ovarian cancer and investigate its therapeutic potential focusing on platinum sensitivity." (PMID 34161330, 2021). "To investigate the role of CHD4 in the outcome among patients with ovarian cancer, we first referred to the TCGA dataset and analyzed the relationship between CHD4 gene alterations and overall survival of the patients." (PMID 34161330, 2021). "In conclusion, we clarified the role of CHD4 in regulation of platinum sensitivity in ovarian cancer cells." (PMID 34161330, 2021). "We have successfully demonstrated the potential of the novel SMARCA5/CHD4 inhibitor ED2-AD10 in combination with cisplatin for the first time in ovarian cancer cells." (PMID 34161330, 2021). "We have also successfully demonstrated the potential of the combination therapy of platinum agents and CHD4 inhibitor by introducing the first-in-class SMARCA5/CHD4 inhibitor ED2-AD101 in ovarian cancer cells." (PMID 34161330, 2021). "Our findings suggest that CHD4 mediates platinum sensitivity by modulating MDR1 expression in ovarian cancer." (PMID 34161330, 2021). "In concordance with these findings, CHD4 knockdown enhanced the induction of apoptosis mediated by cisplatin in ovarian cancer cells TOV21G and increased cisplatin sensitivity in multiple ovarian cancer cells derived from different subtypes." (PMID 34161330, 2021). "In this study, we clarified that CHD4 was involved in platinum sensitivity in ovarian cancer by positively regulating MDR1 expression." (PMID 34161330, 2021). "CHD4 mRNA expression was significantly higher in platinum-resistant samples in a subsequent clinical sample analysis, suggesting that CHD4 overexpression conferred platinum resistance to ovarian cancer cells, resulting in poor patient survival." (PMID 34161330, 2021). "Although the feasibility should be assessed further, CHD4 has the potential to bring benefits to patients with ovarian cancer." (PMID 34161330, 2021). "The response varied among cell lines, indicating that the combination of treatment with platinum agents and CHD4 suppression was a more promising therapeutic strategy for ovarian cancer than CHD4 inhibition alone." (PMID 34161330, 2021). "The results with ED2-AD101 successfully validated the potential of CHD4 as a novel therapeutic target in ovarian cancer cells in combination with cisplatin." (PMID 34161330, 2021). "The purpose of this study was to elucidate the potential of CHD4 as a new therapeutic target for the treatment of ovarian cancer, with a particular focus on its interaction with platinum agents." (PMID 34161330, 2021).
ovarian carcinoma (continued). "Overall, CHD4 plays a vital role in the maintenance of ovarian cancer in vitro and in vivo." (PMID 40004553, 2025). "All these results demonstrate that CHD4 acts as an oncogene in ovarian cancer." (PMID 36681835, 2023). "For this purpose, we examined the EZH2 protein level in CHD4 knockdown ovarian cancer cells." (PMID 36681835, 2023). "It is important to consider whether the silencing of CHD4 may influence the biological behaviour of ovarian cancer." (PMID 36681835, 2023). "Taken together, these studies imply that CHD4 may support the progression of ovarian cancer by regulating the cellular histone status via HDAC or the DNA damage response via PARP." (PMID 36681835, 2023). "Herein, our data indicate that CHD4 cooperates with EZH2 in ovarian cancer to exert its key roles and that these roles may be mediated in part by Wnt/β-catenin pathway activation." (PMID 36681835, 2023). "The HDAC1/2i romidepsin attenuates the prometastatic effect of CHD4 in ovarian cancer, which indicates that the prometastatic effect of CHD4 may be realized via histone deacetylation." (PMID 36681835, 2023). "In addition, we further used GSEA to analyse the potential pathway involved in CHD4-mediated inhibition of ovarian cancer." (PMID 36681835, 2023). "Accordingly, we showed that CHD4 could inhibit the metastasis of ovarian cancer using a mouse model." (PMID 36681835, 2023). "In vitro, we found that romidepsin suppresses the prometastatic effect of CHD4 in ovarian cancer, which indicates that the prometastatic effect of CHD4 may be realized via histone deacetylation." (PMID 36681835, 2023). "CHD4 also confers antimetastatic effects on ovarian cancer cells and prevents disease progression." (PMID 36681835, 2023). "In concordance with our hypothesis, the results revealed that CHD4 expression regulated platinum sensitivity in ovarian cancer cells." (PMID 34161330, 2021). "The results from the clinical data analysis led us to hypothesize that CHD4 expression possibly influences patient prognosis by regulating platinum sensitivity in ovarian cancer." (PMID 34161330, 2021). "Thus, we next examined the expression of RAD51 and p21 under CHD4 knockdown in two ovarian cancer cells, TOV21G, and JHOC5." (PMID 34161330, 2021). "Chromodomain helicase DNA binding protein 4 (CHD4) is another core component of the NuRD complex and mainly plays a role in cancer by participating in histone deacetylation and PARP-dependent DNA damage repair, which is frequently mutated in ovarian carcinomas." (PMID 37894746, 2023). "Notably, CHD4 depletion sharply reduced the viability (p < 0.05 at 48 h; p < 0.001 at 72 h and 96 h) and metastasis-related behaviour of ovarian cancer cells, suggesting that CHD4 is required to maintain the metastases of ovarian cancer cells." (PMID 36681835, 2023). "Certainly, these findings indicate that CHD4 may have an oncogenic role in ovarian cancer." (PMID 36681835, 2023). "In the current study, we presented the mechanisms by which CHD4, in the context of the NuRD complex, induces a robust metastasis-promoting effect by modulating Wnt/β-catenin signalling and highlighted the therapeutic significance of CHD4 as a novel oncogene in ovarian cancer." (PMID 36681835, 2023). "Interestingly, however, CHD4 expression was significantly higher in platinum-resistant cases (p = 0.033), suggesting that CHD4 overexpression had the potential to lead platinum resistance in patients with ovarian cancer." (PMID 34161330, 2021). "Recent studies suggest that by modulating the HDAC function, CHD4 alters cellular histone status, alters the PARP-mediated DNA damage response, and sequentially promotes the progression of ovarian cancer." (PMID 40004553, 2025). "We next analysed the relationship between CHD4 and methylation enzymes (DNMT1, DNMT3B, EZH2, and G9a) in ovarian cancer." (PMID 36681835, 2023).
ovarian carcinoma (continued). "Knockdown of CHD4 reduces the expression of multi-drug efflux transporter ATP-binding cassette ABCB1 or multi-drug resistance-1 (MDR1) in ovarian cancer cell lines (TOV21G and JHOG5); this suggests that CHD4 modulates the function of MDR1 and plays a vital role in ovarian cancer." (PMID 40004553, 2025). "To explore whether EZH2 is necessary for the inhibitory effect of CHD4 on ovarian cancer, we overexpressed EZH2 in a CHD4 knockdown OC cell line." (PMID 36681835, 2023). "The clinical significance of EZH2 prompted us to experimentally assess whether CHD4 and EZH2 are correlated in ovarian cancer." (PMID 36681835, 2023). "CHD4 mRNA expression was 18.9-fold higher in ovarian cancer tissue than in nontumor tissue (p < 0.0001)." (PMID 36681835, 2023). "The TCGA cohort of OC patients was used to examine the mRNA expression of CHD4 in ovarian cancer tissue compared to nontumor tissue." (PMID 36681835, 2023). "Contrary to our expectation, the expression of RAD51 or p21, which are the known targets of CHD4 as it was shown in other cancer types, was not clearly affected by CHD4 knockdown in the ovarian cancer cells we tested." (PMID 34161330, 2021). "However, the importance of CHD4 in ovarian cancer has not been fully studied." (PMID 34161330, 2021).
colorectal cancer (12 papers, 2018 to 2025). A primary or metastatic malignant neoplasm that affects the colon or rectum. "Loss of CHD4 expression was found in 56.4% of gastric cancers and in 55.7% of colorectal cancers, whereas CHD8 was mutated in 35.7% of gastric cancers and in 28.6% of colorectal cancers." (PMID 37175555, 2023). "The CHD4 gene has a crucial role in colorectal cancer, and it is important to consider the activity of this gene to establish a treatment for colorectal cancer patients." (PMID 34142021, 2021). "In colorectal cancer, CHD4 activates the recruitment of DNA methyltransferases (DNMTs) to tumor suppressor gene promoters and inhibits their expression and stimulates tumorigenesis." (PMID 33419089, 2021). "Overexpression of CHD4 led to pronounced radiotherapy-resistance by maintaining DNA hypermethylation transcription silencing on colorectal cancer patients." (PMID 34142021, 2021). "CHD4 knockdown activates silenced TSGs, which represses colorectal cancer cell proliferation, invasion and metastasis." (PMID 32228507, 2020). "In colorectal cancer, high CHD4 correlates with early disease recurrence and decreased overall survival." (PMID 32228507, 2020). "Clinically, CHD4 overexpression is associated with worse outcome in glioblastoma, non-small-cell lung cancer (NSCLC), hepatocellular carcinoma, rectal cancer, triple negative breast cancer and colorectal cancer." (PMID 33419089, 2021). "In colorectal cancer (CRC) cells, CHD4 is one of the most significantly upregulated genes among all subunits of the NuRD complex." (PMID 36681835, 2023). "An oncogenic role for CHD4 has been defined in initiating and supporting tumor suppressor gene (TSG) silencing in human colorectal cancer." (PMID 33981601, 2021).
dermatomyositis (10 papers, 2012 to 2025). Dermatomyositis (DM) is a type of idiopathic inflammatory myopathy characterized by evocative skin lesions and symmetrical proximal muscle weakness. "CHD4 is a known target of autoantibodies in the inflammatory myopathy called dermatomyositis, where anti-CHD4 positivity is associated with more severe muscle disease." (PMID 40026247, 2025). "Of passing interest to rheumatologists, CHD4 is one of the target antigens for anti‐Mi2 autoantibodies, which are found in ~20% of patients with dermatomyositis." (PMID 33369221, 2021). "Chromodomain helicase DNA binding protein 4 (CHD4), also known as Mi2b, belongs to the SNF2 family of helicases and was first identified as a dermatomyositis-specific auto antigen." (PMID 25326197, 2015). "Chromodomain helicase DNA binding protein 4 (CHD4), also known as Mi2β, belongs to the SNF2 family of helicases and was first identified as a dermatomyositis-specific autoantigen." (PMID 22749909, 2012).
glioblastoma (8 papers, 2017 to 2025). The most malignant astrocytic tumor (WHO grade IV). "CHD4 dysregulation has been studied in various cancer types including glioblastoma, breast, colorectal, lung and rectal cancer." (PMID 33419089, 2021). "Besides FP-RMS, in glioblastoma, CHD4 co-localizes with the transcription factor ZFHX4 and co-regulates a subset of its target genes to maintain the tumor-initiating cell population." (PMID 32744500, 2020).
hepatocellular carcinoma (8 papers, 2019 to 2025). A malignant tumor that arises from hepatocytes. "A high expression of CHD4 has been associated with poor prognosis in non-small-cell lung cancer and hepatocellular carcinoma." (PMID 31438571, 2019). "In the context of CHD4-targeting drugs, recently, Ch41, a novel inhibitor of CHD4, was shown to inhibit the growth of lung tumors and hepatocellular carcinomas in immunocompetent C57BL/6 mice, but it was impaired in immunodeficient C57BL/6 mice." (PMID 40004553, 2025). "In conclusion, our data demonstrate that the CHD4/NuRD complex plays an oncogenic role in human hepatocellular carcinoma." (PMID 32070428, 2020). "For example, CHD4 has been shown to regulate EpCAM+ liver cancer stem cells and chemoresistance in human hepatocellular carcinoma, supporting the hypothesis that the NuRD complex regulates oncogenesis via multiple mechanisms." (PMID 32070428, 2020). "Knockdown of CHD4 in human hepatocellular carcinoma (HCC) cells inhibited cell migration and invasion." (PMID 36681835, 2023). "Given the fact that methylated H3K4 and acetylated H4 are generally associated with active chromatin while methylated H3K9 is generally associated with inactive chromatin, our data indicates that the CHD4/NuRD complex may suppress transcription globally in hepatocellular carcinoma." (PMID 32070428, 2020). "It is also demonstrated that the CHD4/NuRD complex facilitates the impairment of CD8+ T cell and DC cell infiltration in hepatocellular carcinoma." (PMID 40004553, 2025). "Importantly, we also found the co-localisation of MBD3 with CHD4 and HDAC1 in human hepatocellular carcinoma samples." (PMID 35501390, 2022). "Therefore, targeting CHD4 may paralyze the complex, leading to deregulation of the target genes, including EMT-related genes and the complement pathway genes, and eventually affect tumorigenesis in hepatocellular carcinoma." (PMID 32070428, 2020).